CEP126 (centrosomal protein 126)
Description:
Participates in cytokinesis. Necessary for microtubules and mitotic spindle organization. Involved in primary cilium formation.
Synonyms: KIAA1377
Tractability: PROTAC: ubiquitination databases record sites on it.
Gene: Protein-coding gene on chromosome 11 (101,915,010 to 102,001,062, forward strand). Ensembl gene ENSG00000110318.
Subcellular location: Midbody; Cytoplasm, cytoskeleton, microtubule organizing center, centrosome; Cytoplasm, cytoskeleton, cilium basal body
Gene Ontology:
Molecular function: protein binding
Biological process: cilium assembly; cytoplasmic microtubule organization; mitotic spindle organization; non-motile cilium assembly
Cellular component: centrosome; ciliary base; midbody
Genetic constraint (gnomAD): Loss-of-function variants: 43 observed, 75.76 expected, observed/expected ratio (o/e) 0.57, 90% interval 0.44 to 0.73. The upper end of that interval is the gene's LOEUF score, 0.73, which puts it in group 2 of 6, group 1 being the genes least tolerant of losing a copy. Missense variants: 1,014 observed, 1,105.2 expected, observed/expected ratio (o/e) 0.92, 90% interval 0.87 to 0.97. Synonymous variants: 379 observed, 393.47 expected, observed/expected ratio (o/e) 0.96, 90% interval 0.88 to 1.05.
Homologues: Orthologues: chimpanzee CEP126 (99% identical), macaque CEP126 (94% identical), pig CEP126 (74% identical), rabbit CEP126 (73% identical), guinea pig CEP126 (71% identical), dog CEP126 (68% identical), mouse Cep126 (60% identical), rat Cep126 (60% identical), tropical clawed frog cep126 (26% identical), zebrafish cep126 (20% identical).
Diseases named in the same sentence as CEP126 in open-access papers:
CEP126 is named in the same sentence as 12 diseases in open-access papers, as found by Europe PMC text mining. Sharing a sentence is not in itself a finding about the gene and the disease. The quoted sentences say what the papers report.
mastitis (1 paper, 2021). Inflammation of breast tissue during lactation or postpartum due to an obstructed duct or infection. "Candidate genes identified in this region were related to both cell division (CEP126 (Centrosomal Protein 126)) and immune cell progenitor differentiation (ANGPTL5 (Angiopoietin like 5), supporting our theory that risk PC1 does indeed reflect both mastitis and udder and teat morphology." (PMID 33920522, 2021).
CEP126 also shares sentences with these, for which no sentence is quoted: tumor (3 papers); cancer (2); esophageal cancer (2); B-cell lymphomas (1); bladder cancer (1); lung carcinoma (1); microcephaly (1); multiple myeloma (1); salivary gland tumours (1); schizophrenia (1); squamous cell carcinoma (1).